PPARA (peroxisome proliferator activated receptor alpha)
Diseases named in the same sentence as PPARA in open-access papers (continued):
Sharing a sentence is not in itself a finding about the gene and the disease.
hyperlipidemia (continued). "Taken together, the STZ-induced mice treated with SA could have normalized hyperlipidemia, including blood TG and TC levels, by a reduction in the expression levels of FAS and mRNA levels of SREBP2 but an increase in expression levels of PPARα in the liver." (PMID 31581697, 2019). "PPARα agonists, such as fibrate, reduce triglyceride levels but not cholesterol levels in the serum of patients with hyperlipidemia." (PMID 30504232, 2019). "Fibrates including gemfibrozil, bezafibrate and fenofibrate are synthetic PPARα agonists that decrease plasma TG levels and increase HDL-cholesterol levels in patients with hyperlipidemia and Type 2 diabetes, thereby preventing coronary heart disease and stroke." (PMID 30041488, 2018). "In conclusion, PPARα activation plays a vital role in regulating lipid metabolism by promoting fatty acid oxidation, improving lipoprotein metabolism, and reducing triglyceride accumulation, thus preventing the onset of conditions like MASLD and hyperlipidemia." (PMID 40926269, 2025). "Short and long-term DOX treatment can induce IR, hyperglycemia, and hyperlipidemia, increase hepatic FFAs contents, stimulate hepatic de novo lipogenesis, and promote NAFLD through several pathways, including stimulating adipose tissue lipolysis by activating PPARα." (PMID 36677854, 2023). "Our results showed that Dp3-Sam treatment increased the CYP7A1, CPT1, ACOX, and PPARα expression in the liver tissue of HFD rats, indicating that Dp3-Sam intervention inhibited lipid accumulation via acceleration of lipid oxidation in HFD-induced hyperlipidemia rats." (PMID 34281481, 2021). "Compared with the HFD group, we found that the mRNA expression levels of PPARα were significantly increased, whereas the gene expression levels of PPARγ were suppressed observably with MDG-1 intervention, implying that MDG-1 could improve hyperlipidemia through regulating PPARs signaling." (PMID 28885549, 2017). "The efficacy of fibrates in the treatment of hyperlipidaemia depends on their ability to activate PPARα However, GW6471, a PPARα antagonist, did not prevent fenofibrate from inhibiting viral infection." (PMID 34421587, 2021).
breast cancer (173 papers, 2005 to 2026). A primary or metastatic malignant neoplasm involving the breast. "Six PPARα polymorphisms are evaluated in association with incident breast cancer, from which rs4253760 is found associated with a nearly 100% relative increase in the risk of postmenopausal breast cancer." (PMID 36589809, 2022). "High expression levels of the protein G0/G1 Switch 2 (G0S2) which regulates lipid metabolism via peroxisome proliferator-activated receptor-α (PPARα) were recently reported to associate with a decrease in breast cancer recurrence rates." (PMID 35911770, 2022). "A deficiency of PPARα in B cells blocked the generation of tBregs, and thus, abrogated lung metastasis in mice with established breast cancer." (PMID 35954274, 2022). "The activation of PPARA has been shown to promote proliferation in human breast cancer and its genetic polymorphism has been linked to an increase in the odds of postmenopausal breast cancer." (PMID 33558504, 2021). "PPARα has been linked to several types of cancer, including breast cancer, hepatocellular carcinoma, chronic lymphocytic leukemia, glioblastoma, and renal cancer." (PMID 31775380, 2019). "The PPARα associated pathway is the top listed Yang pathway TNBC but is also one of the pathways with similar significance shared with other breast cancer subtypes." (PMID 29301506, 2018). "PPARα activation increases proliferation in breast cancer cell lines and in renal cell carcinoma cell line and causes liver cancer in rodents, while PPARα null-mice are shown to be resistant to hepatocarcinogenic effects of PPARα agonists." (PMID 29312541, 2017). "ER + breast cancer patient RNAseq data from TCGA revealed an association of ROS and PPAR signaling with NNAT expression and in silico analysis of the NNAT promotor revealed consensus binding sites for NRF1 and PPARα/PPARγ, as well as the cell cycle transcription factor, E2F4." (PMID 37400769, 2023). "Knockdown of PPARα has been associated with reduced breast cancer-specific survival." (PMID 38189049, 2023). "This suggests that PPARα signaling is linked to the active FAO phenotype in breast cancer cells." (PMID 31996743, 2020). "Interestingly, eight genes (ID4, LTBP4, GPM6B, RGMA, EFCAB1, ALX4, OSR1 and PPARA) were confirmed to be down-expressed in breast cancer tissues, and associated with the overall survival time of breast cancer patients, as high expression of these genes correlate with an improved prognosis." (PMID 32650755, 2020). "Clofibrate attenuated the inflammatory response by activating the PPARα pathway to inhibit the growth of human breast cancer cells." (PMID 38526709, 2025). "It serves as an independent prognostic marker in breast cancer, disrupts PPARα/γ signaling in prostate cancer, and promotes proliferation and senescence resistance in colorectal cancer." (PMID 41208974, 2025). "For example, an elegant study on breast cancer demonstrated that PPARA expression in B cells promoted their transformation into tBregs, a unique type of regulatory B cells able to convert CD4 T cells into Tregs with prometastatic capability." (PMID 41148824, 2025). "Our study lays the foundation for future research on PPARα-targeted therapeutics for fatty acid metabolism in breast cancer treatment." (PMID 39859448, 2025). "The regulatory mechanism of FAO in breast cancer has attracted considerable attention, with PPARα identified as a major regulator." (PMID 40002245, 2025). "In this context, we explored how breast cancer cells modify their fatty acid metabolism, focusing on the importance of PPARα-targeted therapeutic approaches for fatty acid metabolism in breast cancer treatment." (PMID 39859448, 2025). "PPARα mediates the regulation of the downstream lipid metabolism pathway via ASCT2 to affect breast cancer growth." (PMID 39272886, 2024). "UA exhibited antiproliferative effects against skin, prostate, and breast cancers, partially via PPARα and RORγ pathways." (PMID 37893218, 2023).
breast cancer (continued). "It has been reported that lipid metabolite of leukotriene B4 produced by breast cancer cells acts as an endogenous PPARα agonist and induces immunosuppressive regulation of B cells (tBregs), thereby promoting distant metastasis of cancer cells." (PMID 37251321, 2023). "In this study, we investigated the activity pattern of the FOXM1 and PPARA pathways in both TCGA breast tumor patient and breast cancer cell line data." (PMID 36424525, 2023). "The normal tissue group from TCGA shows a significantly higher PPARA pathway activity score than each of the four breast cancer tissue groups." (PMID 36424525, 2023). "In breast cancer stem cells, the PPARα antagonist GW6471 has anti-proliferation and pro-apoptotic effects while the PPARα agonist Wy14643 promotes clonal expansion through NF-κB/IL-6 axis signaling activity promotion." (PMID 38189049, 2023). "Our previous studies demonstrated that the FOXM1 pathway is upregulated and the PPARA pathway downregulated in breast cancer (BC), and especially in the triple negative breast cancer (TNBC) subtype." (PMID 36424525, 2023). "Activated PPARα had the most significant pro-proliferation effect on ER+ MCF7 cells.Although the effect of PPARβ/δ on the proliferation of breast cancer cells is highly controversial, its effect on ER+ and ER- cells is indeed different." (PMID 36611922, 2022). "Fenofibrate induces apoptosis of triple-negative breast cancer cells via activation of the NF-κB pathway, and Wy14643 shows toxicity to breast cancer cells via PPARα–CYP1B1 expression, suggesting the therapy potential of PPARα in breast cancer." (PMID 36589809, 2022). "Our results indicated that RUNX2/NuRD(MTA1)/CRL4B complex suppressed invasion, migration, and bone metastasis of breast cancer cells through inhibiting PPARα." (PMID 35534547, 2022). "Leptin and glucose treatment stimulated breast cancer proliferation, which was accompanied by an upregulation of PPARα, suggesting the involvement of PPARα in this process." (PMID 35954274, 2022). "This complex catalyzed histone deacetylation and ubiquitination, inhibited the transcriptional activity of target genes, including PPARα, and promoted the proliferation and invasion of breast cancer cells in vitro." (PMID 36611922, 2022). "PPARα expression has been demonstrated in human breast cancer cell lines, which showed increased proliferation upon PPARα activation." (PMID 35954274, 2022). "Kaplan–Meier survival analysis revealed that higher expression of PPARα and SOD2 was associated with improved survival of breast cancer patients." (PMID 35534547, 2022). "It was also reported that CPT1A and CPT2—known target genes of PPARα—are involved in the radiation resistance of breast cancer stem cells and overall survival of breast cancer." (PMID 33466690, 2021). "This later showed that THC not only increases the expression of fatty acid 2-hydroxylase (FA2H) via the upregulation of PPARα expression in human breast cancer MDA-MB-231 cells but that THC also interferes with the PPARβ/δ-mediated inhibition of PPARα." (PMID 33498245, 2021). "Several studies have elucidated the antitumor effect of PPARA in various cancers, including breast cancer, prostate cancer, and ovarian cancer." (PMID 33959155, 2021). "Considering the exposed evidence, in the present study, breast cancer stem cells were isolated and characterized for the stemness markers and the presence of PPARs and then treated with the potent specific PPARα antagonist, GW6471." (PMID 33525605, 2021). "WY-14643, a PPARα agonist, has been shown to increase the protein and mRNA levels of CYP1B1 in MCF-7 cells via PPARα-dependent mechanism, playing a critical role in the progression of human breast cancer." (PMID 33185690, 2020). "The PPARα agonist, WY-14643, has proinflammatory activity, and some PPARα agonists have been shown to promote the proliferation of breast cancer cells." (PMID 31775380, 2019).
breast cancer (continued). "PPARα is important in several malignant tumors, including breast cancer, hepatocellular carcinoma, chronic lymphocytic leukemia, glioblastoma, and renal cancer." (PMID 31775380, 2019). "PPARα is the top listed TNBC Yang pathway but is a pathway shared with the other breast cancer subtypes." (PMID 29301506, 2018). "There has been evidence that therapies combining PPARα and RXRα ligands in the treatment of breast cancer are effective." (PMID 29301506, 2018). "The nuclear localization of PPARα suggests that it is transcriptionally active and influences GSCs proliferation, as observed also in breast cancer cell lines." (PMID 29312541, 2017). "Hawthorn polyphenol extract suppresses the fatty acid synthetase gene in breast cancer cells and stimulates fat oxidation through the activation of peroxisome proliferator–activated receptor alpha (PPAR α) in hamsters fed a high-fat diet." (PMID 27187458, 2016). "Collectively these results highlight the presence of PPARα expression in human breast cancer tissues." (PMID 26621841, 2016). "In conclusion, we have demonstrated that activation of PPARα via its agonist clofibrate downregulates the inflammatory and lipogenic pathways along with suppressing the growth of human breast cancer cells." (PMID 26621841, 2016). "To extend our previous in vitro observations, we analyzed the breast tissue sections of healthy subjects and breast cancer patients for the presence of PPARα by immunofluorescence staining using anti-PPARα antibody." (PMID 26621841, 2016). "Since we observed higher levels of PPARα in breast cancer cells versus HMEC cells, we next evaluated the effect of clofibrate treatment on COX-2 inflammatory pathway enzymes and their receptors in breast cancer cells." (PMID 26621841, 2016). "Activation of PPARα in breast cancer cells suppressed inflammatory COX-2 and 5LO activity and resulted in decreased PGE2 and LTB4 secretion as well as a reduction in PGE2 and LTB4 receptor expression." (PMID 26621841, 2016). "Abundant PPARα expression was detected in breast cancer tissue sections compared to the normal healthy control tissue sections." (PMID 26621841, 2016). "The data presented here demonstrate that cyclin D1, an important cell cycle control protein and proto- oncogene, inhibits PPARα-mediated gene expression and FA oxidation in both hepatocytes and cell lines derived from hepatocellular and breast cancer." (PMID 27351284, 2016). "There was a consistent high expression of PPARα in the breast cancer tissue samples (panels a1, b1, d1, e1, e2, a3, b3, d3, a4, b4, d4, a5, a7, a8, b8, d8, and e8) when compared to the normal healthy control tissue samples counterparts in panels c and f." (PMID 26621841, 2016). "In this study, we made several interesting findings in the context of PPARα nuclear receptor signaling, lipogenic, and inflammatory pathways in inflammatory and invasive breast cancer cells." (PMID 26621841, 2016). "In liver and breast cancer cells, knockdown of cyclin D1 leads to increased PPARα transcriptional activity, expression of PPARα target genes, and fatty acid oxidation." (PMID 27351284, 2016). "We demonstrated that PPARα activation decreased the growth rate of breast cancer cells via reducing the level of various cell-cycle regulating cyclins." (PMID 26621841, 2016). "Reduction of SREBP-1c upon clofibrate treatment in breast cancer cells further adds to the anti-lipogenic potential of PPARα nuclear receptor signaling pathway." (PMID 26621841, 2016). "On the other hand, activation of PPARα has been shown to increase proliferation in breast cancer cell lines." (PMID 23951092, 2013). "Our data demonstrate the importance of exploring the role of nuclear receptors (PPARα/PPARγ) in the regulation of pro-inflammatory pathways, with the aim to thwart breast cancer stem cells functioning." (PMID 23372804, 2013).
breast cancer (continued). "To examine potential synergistic effects of synthetic PPAR and RXR ligands on these lines, we treated human breast cancer cells with the PPARα agonist clofibrate, the PPARγ selective ligand ciglitazone, and the RXR selective agonist AGN194204." (PMID 21080969, 2010). "PPARα activation by clofibrate has been shown to increase proliferation of breast cancer cells and of normal rat mammary gland in vivo." (PMID 21080969, 2010). "We previously demonstrated that human breast cancer cell lines expressed PPARα and PPARγ, and their lipid ligands inhibited proliferation of these cells." (PMID 21080969, 2010). "It is well documented that in mammary cancer cells PPARα is over-expressed, and its activation correlates with proliferation." (PMID 19500378, 2009). "The genetic interaction STAT5A → PPARA was among those selected, as in the case of the Dutch breast cancer data set." (PMID 18358079, 2008). "MK866 blocks the 5-lipoxygenase pathway of arachidonic acidmetabolism, increases the expression of PPARα and PPARγ in breast cancer cells, and induces apoptosis.As well, in lung cancer cells, MK886 increased PPARγ reporter activity." (PMID 18615184, 2008). "On the other hand, one recent study pointed at PPARα as a possiblecontributor to the growth inhibitory effect of n-6 PUFA arachidonic acidexerted in the same pair of breast carcinomas cell lines." (PMID 18645617, 2008). "In our study, all three PAEs showed a strong and stable binding with ESR1 and PPARA through strong binding force or extensive hydrogen bonding assistance, suggesting that these receptors may be primary targets through which breast cancer is promoted." (PMID 41155171, 2025). "Furthermore, the addition of leptin and glucose enhances breast cancer cell proliferation and upregulates PPARα, thereby indicating the involvement of PPARα in this process." (PMID 39859448, 2025). "Additionally, C118P can regulate the expression of PPARα to inhibit the lipid metabolism pathway and the growth of basal-like breast cancer by targeting ASCT2." (PMID 39272886, 2024). "The PPARA pathwaywas suppressed in breast cancer expression, specifically in subtypes of TNBC." (PMID 38329441, 2024). "The genes regulated by PPARα can determine their cancer-promoting or cancer-suppressing effects due to their relationship with tumor metabolism; for example, inhibitory and promoting effects have been reported in melanoma and breast cancer, respectively." (PMID 37251321, 2023). "The chemical sensitivity of breast cancer cells to the PPARα agonist clofibrate was high." (PMID 38189049, 2023). "PPARα has high expression in human breast cancer cells and tissues." (PMID 36611922, 2022). "The correlation between PPARα and breast cancer is worth further investigation." (PMID 36611922, 2022). "The growth of three breast cancer cells, MDA-MB-231 (ER-), MCF7 (ER++++), and BT-474 (ER++), were stimulated by AA, with the most pronounced pro-proliferative effect on MCF7 cells, revealing a positive correlation between PPARα and the proliferation of ER+ breast cancer cells." (PMID 36611922, 2022). "Similarly, experiments with RUNX2 depletion indicated that the inhibition of bone metastasis in breast cancer cells by knockdown of PPARα was dependent on RUNX2, at least partially." (PMID 35534547, 2022). "In breast cancer, the role of PPARα also seems bidirectional." (PMID 36589809, 2022). "Similarly, arachidonic acid (AA) has been found to promote breast cancer cell proliferation through the activation of PPARα." (PMID 35954274, 2022). "High glucose activated PPARα and PPARγ expression in breast cancer cell cultures." (PMID 35954274, 2022). "We found that RUNX2 knockdown increased epithelial markers and decreased mesenchymal marker expression, which was partially rescued via the co-knockdown of PPARα, indicating that RUNX2 could promote breast cancer cells invasion by repressing PPARα expression." (PMID 35534547, 2022).